NEDD4 (NEDD4 E3 ubiquitin protein ligase)
Diseases named in the same sentence as NEDD4 in open-access papers (continued):
Sharing a sentence is not in itself a finding about the gene and the disease.
infection (20 papers, 2009 to 2025). The state of being infected such as from the introduction of a foreign agent such as serum, vaccine, antigenic substance or organism. "The decreased susceptibility of KO cells was returned to WT levels of infection upon NEDD4 reconstitution." (PMID 26263374, 2015). "We observed that NEDD4 KO MEFs were in fact significantly less susceptible to infections with influenza A virus (IAV) subtypes H1N1 and H3N2 (PR8 and X-31 strains, respectively) compared to WT control cells." (PMID 26263374, 2015). "NEDD4 KO cells were significantly less susceptible than WT cells to infection by both influenza B virus (IBV) and IAV H3N2 strains isolated in 2011." (PMID 26263374, 2015). "Infection caused Nedd4-GFP to accumulate in the perinuclear region, and in addition, Nedd4 was also distributed in a vesicular pattern in the peripheral of the cytoplasm." (PMID 19835589, 2009). "Importantly, knockdown of IFITM3 in both NEDD4 WT and KO MEFs resulted in an increase in influenza virus susceptibility, and largely eliminated the resistance of NEDD4 KO cells to infection." (PMID 26263374, 2015). "In the context of Japanese encephalitis virus (JEV), down-regulation of NEDD4 led to a notable inhibition of infection." (PMID 40788667, 2025). "Calcium ion concentration gradually increases 4-24h after Brucella infection of cells, Calpain2 binds to Nedd4 and is ubiquitinated at 24h post-infection." (PMID 39507949, 2024). "Calpain-2 is ubiquitinated by Nedd4, after infection with B. abortus, and degraded as intracellular calcium increases." (PMID 37143745, 2023). "Nedd4 shRNA was highly effective in knocking down endogenous Nedd4 expression 7 days after infection." (PMID 31373553, 2019). "Because cells that had been depleted for NEDD4 or MARCH8 displayed low permissiveness to infection by HIV-1, these analyses were performed using IF and flow-cytometry analyses to allow identification of infected cells." (PMID 28320822, 2017). "Heightened IFITM3 levels significantly protected NEDD4 knockout cells from infection by influenza A and B viruses." (PMID 26263374, 2015). "To confirm that the increased resistance of NEDD4 KO cells to influenza virus infection was due to increased levels of basal IFITM3, we knocked down IFITM3 in NEDD4 WT and KO cells for 24 hours prior to infection." (PMID 26263374, 2015). "Overall, our study identifies inhibition of NEDD4 as a novel strategy for preventing infection by influenza virus and other IFITM3-sensitive viruses through the increased accumulation of the antiviral restriction factor IFITM3." (PMID 26263374, 2015). "Upon infection of sN1 cells with NEDD4–3′UTR shRNA (TRCN0000272425) expression virus, which suppresses endogenous NEDD4 only, invasive ability was maintained." (PMID 25823820, 2015). "Consistent with a role for Nedd4 in HIV infection, intra-rectal challenge of rhesus macaques with SHIVSF162P3 demonstrated an increase in Nedd4 protein post-infection." (PMID 24614057, 2014). "In this study, we investigated post-transcriptional changes of Nedd4 following SHIVSF162P3 infection of rhesus macaques, its role on HIV-1 p24 and gp120 levels in vitro and its potential as an immune modulator in HIV vaccination of BALB/c mice." (PMID 24614057, 2014). "Ongoing studies seek to understand the pathways involved in such Nedd4 modulation and if other E3 ligases are induced post infection with HIV/SIV/SHIV." (PMID 24614057, 2014). "Here, we also observed substantial increases in the mRNA expression of different HECT E3 ligases, specifically WWP1, WWP2, SMURF1 and NEDD4, in infected Vero E6 and Calu-3a cells, which could exacerbate infection." (PMID 36754974, 2023). "Conversely, Nedd4 ubiquitin ligases were critical during infection suggesting that the most important contribution made to virus release by Nedd4 ligases is not direct ubiquitination of the viral matrix protein, but possibly the ubiquitination of cellular proteins or other viral proteins." (PMID 31710650, 2019).
infection (continued). "However, it is possible that the CRL3, VI and Nedd4 proteins target different Daxx functions during early time of the infection." (PMID 24260437, 2013). "Here we demonstrated that WWP1, WWP2, and NEDD4 are overexpressed during SARS-CoV-2 infection and that their expression co-localizes with areas of infection in lung tissue both in mice and humans." (PMID 33762578, 2021). "Further functional analysis showed that Nedd4 attenuated JEV-induced autophagy, which negatively regulates virus replication during infection." (PMID 28349961, 2017). "Depleting NEDD4 from cells results in IFITM3 accumulation and greater resistance to infection by influenza viruses." (PMID 26263374, 2015). "We here identify increased Nedd4 protein levels in both CD4+ and CD8+ T cells following SHIVSF162P3-infection of naïve macaques." (PMID 24614057, 2014). "Increased Nedd4 protein levels were noted in both CD4+ and CD8+ T cells following SHIVSF162P3-infection of naïve macaques." (PMID 24614057, 2014). "If HSV-2 exploited MVBs and/or late endosomes for assembly or release of virions, and if Nedd4 and UL56 were involved in the process, a greater amount of Nedd4 and UL56 should colocalize with CD63 as the infection proceeds." (PMID 19835589, 2009). "The RGNNV infection significantly increased the formation of exosomes, and subsequently, the expression of exosome-related proteins, including ALIX, CD63, Nedd4, and TSG101, was increased as well." (PMID 39494909, 2024). "Although expression of this transcript peaked at 72 hr of infection, it was nevertheless clearly detectable at early time points, suggesting that UL42 protein is likely to be expressed contemporaneously with degradation of NEDD4 and NEDD4L." (PMID 31873071, 2019). "The third employed an unbiased global pulse-chase to compare the rates of protein degradation during HCMV infection against mock infection (NEDD4 and NEDD4L were not quantified in this latter screen)." (PMID 31873071, 2019). "Similar to the JEV internalization assay, the infection of JEVpv was not impaired by the knockdown of Nedd4." (PMID 28349961, 2017). "Overall, this work identifies the enzyme NEDD4 as a new therapeutic target for the prevention of influenza virus infections, and introduces a new paradigm for up-regulating cellular levels of IFITM3 independently of IFN or infection." (PMID 26263374, 2015). "We hypothesized that if Nedd4 plays a key role in HIV pathogenesis, induction of Nedd4 would be observed post-infection of rhesus macaques with Simian-Human Immunodeficiency Virus and/or Simian Immunodeficiency Virus." (PMID 24614057, 2014). "Alternatively, we cannot rule out the possibility that early induction of Nedd4 and other E3 ligases represents, in-part, a host antiviral response that is exploited by the virus to mediate increased replication, budding and infection." (PMID 24614057, 2014). "Furthermore, infection with the CSPwt parasite, but not the CSPmut parasite, significantly elevated the mRNA level of NEDD4 in HepG2 cells, strongly suggesting that the translocation of CSP from the PV into the cytoplasm could upregulate the expression of E3 ubiquitin ligase NEDD4." (PMID 35222391, 2022).
cardiovascular disease (4 papers, 2020 to 2024). "NEDD4 is thought to be implicated in various human diseases, from cardiovascular disease (Liddle’s syndrome) to cancers." (PMID 36825281, 2023). "Mechanistically, Tudor-SN was found to regulate the degradation of PTEN, a well-known tumor suppressor protein that also has critical functions in cardiovascular diseases, via NEDD4-1, an established E3 ubiquitin ligase for PTEN." (PMID 39237902, 2024). "NEDD4 quantification in clinical samples would also constitute an important method for determining NEDD4 significance in cardiovascular disease." (PMID 33110392, 2020). "NEDD4 proteins identify different substrate proteins to perform ubiquitination catalysis, thus participating in various cardiovascular diseases." (PMID 33110392, 2020). "Recently, ubiquitination as an important protein post-translational modification has been demonstrated to be closely related to cardiovascular disease, and Nedd4 as the key enzyme in ubiquitination has been found to be involved in the regulation of myocardial regeneration and repair." (PMID 35858921, 2022).
kidney disease (2 papers, 2020 to 2021). "In the Nedd4-2Ksp1.3 model of kidney disease, mRNA expression of Wnt ligands were generally increased, with activation of distinct subsets of ligands sustained by high Na+, culminating in β-catenin upregulation." (PMID 33854040, 2021). "Upregulation of pSMAD2 and pSMAD3 in this study implicates this pathway in kidney disease in Nedd4-2Ksp1.3 mice, particularly after high Na+." (PMID 33854040, 2021). "Together, results from this study suggest that ENaC is the primary contributor to the salt-sensitivity of kidney disease in Nedd4-2Ksp1.3 mice." (PMID 31802037, 2020).
neurodegenerative disease (2 papers, 2022 to 2023). A disorder of the central nervous system characterized by gradual and progressive loss of neural tissue and neurologic function. "Research on NEDD4 proteins in neurodegenerative diseases remains an exciting field in which many surprising findings can still be expected." (PMID 35328067, 2022). "The regulation, function, and substrate specificity of NEDD4-1 and NEDD4-2 need to be studied in vivo in a tissue- and cell-type-specific fashion before strategies can be designed to propose them as therapeutic targets for neurodegenerative diseases such as PD." (PMID 35328067, 2022).
neurodevelopmental disorder (2 papers, 2021 to 2025). A behavioral and cognitive disorder with onset during the developmental period that involves impaired or aberrant development of intellectual, motor, or social functions. "Genetic variants of NEDD4 have also been identified in patients with neurodevelopmental disorders." (PMID 40299435, 2025). "Understanding the molecular mechanism linking activity-dependent degradation of GluA2 and the SUSD4/NEDD4 complex will thus be of particular importance for our understanding of the etiology of these neurodevelopmental disorders." (PMID 33661101, 2021).
digestive diseases (1 paper, 2024). "In recent years, the relationship between the subfamily of neuron-expressed developmental downregulation 4 (NEDD4), which belongs to the E3 ligase system, and digestive diseases has drawn widespread attention." (PMID 38785984, 2024). "In recent years, the relationship between NEDD4/NEDD4L and digestive diseases has become a hotspot research topic." (PMID 38785984, 2024). "In this paper, we reviewed the roles of NEDD4 and NEDD4L in various digestive diseases for the purpose of providing new strategies for the prevention and treatment of digestive diseases." (PMID 38785984, 2024). "Specifically, NEDD4 and NEDD4L, as the major E3 ligases of the NEDD4 family, are critical in a variety of pathophysiological processes in digestive diseases and are involved in disease development by mediating the ubiquitination degradation of PTEN, c-Myc, and P21." (PMID 38785984, 2024).
metabolic disease (1 paper, 2025). A congenital disorder (due to inherited enzyme abnormality) or acquired (due to failure of a metabolically important organ) disorder resulting from an abnormal metabolic process. "NEDD4 suppression ameliorates metabolic disease phenotypes, such as increased lipolytic activity, decreased body weight and improved insulin tolerance, in HFD-fed mice." (PMID 39900792, 2025).
psychiatric disorder (1 paper, 2021). A disorder characterized by behavioral and/or psychological abnormalities, often accompanied by physical symptoms. "However, given the limitations of our study, the relation between NEDD4 and psychiatric disorders still needs to be explored further, and the impact of its interaction with CT on clinical symptoms still requires further confirmation by more clinical studies." (PMID 33897484, 2021).
NEDD4 also shares sentences with these, for which no sentence is quoted: skin cancer (3 papers); breast (2); diabetic kidney disease (2); hearing loss (2); Huntington disease (2); Parkinson’s (2); renal fibrosis (2); synovial sarcoma (2); acute myeloid leukemia (1); age-related hearing loss (1); amyotrophic lateral sclerosis (1); autism (1); Azoospermia (1); cerebrovascular disease (1); cervical cancer (1); Cognitive impairment (1); diabetic retinopathy (1); Ebola (1); endometrial adenocarcinoma (1); esophagus cancer (1); experimental autoimmune encephalomyelitis (1); helminth infections (1); idiopathic pulmonary fibrosis (1); invasive breast carcinoma (1); invasive ductal carcinoma (1); Japanese encephalitis (1); kidney cancer (1); lung injury (1); malignant glioma (1); mesothelioma (1).
A further 16 diseases each share a sentence with NEDD4 in 1 paper.